NLRP3 (NLR family pyrin domain containing 3)
Diseases named in the same sentence as NLRP3 in open-access papers (continued):
Sharing a sentence is not in itself a finding about the gene and the disease.
colon carcinoma (continued). "So far, these studies suggest that NLRP3 inflammasome mediates colon cancer migration and invasion." (PMID 39769450, 2024). "Indeed, immunostaining of mouse colonic tumors shows that NLRP3 forms specks in transformed epithelial cells, and less frequently, in tumor-infiltrating CD11b+ myeloid cells." (PMID 38898209, 2024). "They demonstrated that TNF-α and transforming growth factor-β1 (TGF-β1) could upregulate NLRP3 expression in colon cancer epithelial cells, contributing to the epithelial-mesenchymal transition process—a critical facet of cancer cell metastasis." (PMID 38317229, 2024). "Notably, treatment with SCA, a selective HDAC2 inhibitor, induced a dose‐dependent upregulation of NLRP3 levels in colon cancer cells." (PMID 38804602, 2024). "NLRP3 inflammasome has previously been shown to mediate the production of IL-18, which increases the tumoricidal activity of natural killer cells against metastatic colon tumor cells in mouse liver." (PMID 37833249, 2023). "The tumor-suppressive function of the NLRP3 inflammasome has mostly been demonstrated for colon cancer where its preventive role is achieved by tumor immunosurveillance, maintaining epithelial integrity, producing mucus and suppressing the proliferation of intestinal epithelial cells." (PMID 36466820, 2022). "NLRP3 promotes the epithelial-mesenchymal transition (EMT) in colon cancer." (PMID 36457716, 2022). "Streptococcus infection could activate the NLRP3 inflammasome and induce IL-1β secretion, which was previously shown to promote colon cancer." (PMID 35865926, 2022). "The up-regulation of NLRP3 in colon cancer may attribute to the activation of NFκB and TGFβ signaling pathways." (PMID 33821998, 2021). "Finally, LXRβ activates NLRP3 inflammasome in colon cancer cells leading to anti-tumoral effect of LXR agonists." (PMID 33716981, 2021). "Various studies have confirmed that the NLRP3-mediated release of IL-18 or IL-1β enhances the malignancy of lymphoma, gastric cancer, breast cancer, colon cancer, and glioblastoma via promoting the proliferation of cancer, immunosuppression, angiogenesis, and metastasis." (PMID 34298833, 2021). "Another study showed that NLRP3 could promote epithelial to mesenchymal transition in colon cancer cells in an inflammasome-independent manner." (PMID 34298833, 2021). "Numerous studies have shown that the NLRP3 inflammasome can resist the formation of colon cancer, further supporting this speculation." (PMID 32347316, 2020). "A recent report consistently demonstrated that LXR ligands could promote the activation of NLRP3 inflammasome in colon cancer cells leading to cell death." (PMID 27779191, 2016). "Therefore, we tested if NLRP3 inflammasomes are activated in sporadic colon cancer." (PMID 38898209, 2024). "Our results show that gut microbiota/NLRP3-mediated activation of GSDMD promotes the development of colorectal tumors, and supports the use of NLRP3 inhibitors to treat colon cancer." (PMID 38898209, 2024). "Inflammasomes have been reportedly activated by NLRP3-ASC-caspase-1, promoting the expression of the downstream factors IL-18 and IL-1β and playing an anti-tumor role in colon cancer." (PMID 35309942, 2022). "We found that NLRP3 and GLUD2 were the most common necroptosis-related gene alteration in colon cancer patients." (PMID 35874811, 2022). "However, it has been shown that Pycard(−/−), Casp1(−/−) mice and Nlrp3(−/−) mice are prone to inflammation associated colon cancer, suggesting that inflammasome activation or induction of pyroptosis restricts, rather than promotes, colon cancer development." (PMID 33941231, 2021).
colon carcinoma (continued). "The tumor-suppressive role of the NLRP3,143,144 AIM2,145,146 and NLRC4147,148 inflammasomes is well documented in colon cancer." (PMID 34210954, 2021). "Similarly, quercetin has been shown to prevent NLRP3 inflammasome in HCT116 and HT29 colon cancer cells and a nude-mouse xenograft model." (PMID 39769450, 2024). "In the landscape of genetic variation of PRGs in colon cancer patients, somatic copy number alterations could be found in 19 PRGs, with ZBP1, GSDMD, AIM2, and NLRP3 having the highest copy number variation (CNV)." (PMID 38553639, 2024). "The research indicates that Sishen Pills and their active metabolites, schisandrin B, schisandrin, evodiamine, and rutaecarpine could affect cell fate by regulating the NLRP3 and Wnt signaling pathways, thus offering a therapeutic role in IBD and colon cancer." (PMID 38650627, 2024). "In addtion, the protein level of NLRP3, ASC, cleaved-caspase-1, mature IL-1β and GSDMD-N in isolated tumors significantly increased after simvastatin treatment, suggesting the induction of simvastatin on pyroptosis in colon cancer in vivo." (PMID 37974278, 2023). "Therefore, NLRP3 and AIM2 were chose to be detected in in-house GBM samples and publicly available IHC data of colon cancer patients." (PMID 34815793, 2021). "Moreover, both innate immune cells and colon cancer cells exhibit expression of TLR4 and NLRP3 inflammatory bodies." (PMID 31754923, 2019). "Together, these results indicate that XLOC_000647 decreases EMT-induced cell invasion by down-regulating NLRP3, which are consistent with previous studies that reported NLRP3 is involved in the regulation of EMT and in turn promotes the metastasis of colon cancer and lung adenocarcinoma." (PMID 29386037, 2018). "In a study conducted using colon cancer cell lines, it was discovered that metformin can suppress inflammatory factors’ expression, regulate the inflammatory microenvironment, and limit the progression of CRC by inhibiting the expression of the NLRP3 inflammasome." (PMID 39684769, 2024). "However, ablation of GSDMD in sporadic colon tumors did not result in altered IL-1α, IL-1β, and IL-18 as well as NLRP3 or ASC speck formation." (PMID 38898209, 2024). "Using S.t-ΔpGlux/pT-ClyA may simultaneously activate TLR4 and NLRP3 signaling pathways, which increase IL-1β expression and enhance inhibition of colon cancer growth without tumor recurrence." (PMID 31754923, 2019). "NLRP3 and IL1B mRNA expression was quantified in 13 matched nontumoral (NT) tissues, primary colon tumor (T) tissues and liver metastasis (M) tissues." (PMID 38486106, 2024). "Interestingly, we found that both NLRP3 and IL1B mRNA levels were significantly upregulated in both primary colon tumor (T) and liver metastasis (M) tissues compared with nontumoral (NT) tissues." (PMID 38486106, 2024).
fibrosis (70 papers, 2010 to 2026). the formation of excess fibrous connective tissue in an organ or tissue in a reparative or reactive process. "NLRP3 expression is increased in SSc skin and NLRP3-deficient mice are resistant to bleomycin-induced fibrosis." (PMID 34487318, 2023). "Fibrosis of left atrium and susceptibility to AF were detected, and expression of NLRP3-TGF-β in left atrial tissue at 22 weeks of age was measured." (PMID 35860690, 2022). "This pattern holds even after stratification of the patients into mild fibrosis and advanced fibrosis, demonstrating that the NLRP3-rs10754558 or another polymorphism in linkage disequilibrium with it possibly has an influence on the processing of pro-IL-1β." (PMID 34161370, 2021). "The results showed that NLRP3 deficiency alleviated the cardiac fibrosis and inflammation induced by ISO." (PMID 32850832, 2020). "The inflammatory effect of NLRP3 inflammasome has been implicated in the development of many chronic liver diseases that lead to fibrosis and cirrhosis." (PMID 32695095, 2020). "The inflammatory effect of NLRP3 inflammasome has been implicated in the development of various chronic liver diseases that lead to fibrosis and cirrhosis." (PMID 32695095, 2020). "The expression of NLRP3 and associated proteins is markedly enhanced in the organs of fibrosis patients." (PMID 33390969, 2020). "Our study further proves the role of TGF-beta-mediated NLRP3 inflammasomes in CKD-related fibrosis and provides evidence to help elucidate the underlying mechanisms of action." (PMID 32117956, 2020). "While activation of NLRP3 is crucial for host defense, its activation has also been associated with many other chronic diseases, including autoinflammatory diseases, gout, Alzheimer’s disease, diabetes, and fibrosis." (PMID 35625564, 2022). "Tranilast has been shown to have positive effects on cardiac fibrosis and remodeling in multiple animals since its discovery as an NLRP3 inhibitor." (PMID 40079000, 2025). "While Pirfenidone (PFD) and Liraglutide (LIR) have shown promise individually in treating fibrosis, their combined effect on autophagy and NLRP3 inflammasome pathways remains largely unexplored." (PMID 41413484, 2025). "NETs induce EMT and NLRP3 inflammasome activation; Pirfenidone inhibits NETosis and alleviates fibrosis." (PMID 41394824, 2025). "First, atelectasis-related mucus plugs can activate NLRP3 inflammasomes, promote the release of proinflammatory cytokines such as IL-1β, and aggravate peribronchiolar fibrosis." (PMID 40654577, 2025). "Similar endothelial involvement was observed in a study on mechanical stretch-induced fibrosis, where ventilator overdistension triggered NLRP3 activation, EndoMT marker shifts, and collagen accumulation." (PMID 41148809, 2025). "Previous studies have shown that NLRP3 regulates renal fibrosis and inflammation by modulating TGF-β1." (PMID 41394140, 2025). "The increased 7α-hydroxy-4-cholesten-3-one (C4) was observed in the CCl4 group, and NLRP3 knockout decreased the C4 level in CCl4-induced fibrosis." (PMID 40689656, 2025). "Together, these findings underscore a critical detrimental role for the NLRP3 inflammasome in driving silica-induced inflammation and unresolving pulmonary damage and fibrosis." (PMID 40119408, 2025). "In our study, IL-1β and NLRP3 expression levels were negatively correlated with MAFLD fibrosis grade, whereas NFS was positively correlated with MAFLD fibrosis grade." (PMID 39179677, 2024). "Fibrosis in these disorders is mostly influenced by the interaction of the NF-κB/NLRP3/caspase-1/IL-1 axis and TGF-β signaling pathway." (PMID 37446339, 2023). "In conclusion, we identified the novel role of the NLRP3 inflammasome in the regulation of EndoMT in bleomycin-induced lung inflammation and fibrosis." (PMID 37958797, 2023).
fibrosis (continued). "Previous studies have revealed the protective effects of blocking the inflammasomes NLRP3 on cardiac dysfunction, such as reducing cardiac fibrosis and preserving contractile function in mice and in patients with cardiac dysfunction." (PMID 36490253, 2022). "Vimentin, the most abundant intermediate filament in the cytoplasm, regulates the activation of NLRP3 inflammasome in the asbestos-induced lung injury and fibrosis model." (PMID 32121297, 2020). "Although the NLRP3 inflammasome is mainly expressed in innate immune cells, there are several reports of inflammasome independent function of NLRP3 in murine fibrosis models." (PMID 32121297, 2020). "Several studies have shown the upstream mechanism by which the NLRP3 inflammasome is activated in animal fibrosis models." (PMID 32121297, 2020). "We demonstrated recently the predominant role of the NLRP3 inflammasome activation and IL-1β expression in the establishment of pulmonary inflammation and fibrosis in mice." (PMID 21858022, 2011). "In general DM, this often presents as non-alcoholic fatty liver disease (NAFLD), defined by excessive hepatic fat accumulation, oxidative stress, and chronic inflammation mediated by cytokines and the NLRP3 inflammasome, potentially progressing to fibrosis and cirrhosis." (PMID 40427455, 2025). "Similarly, Masson trichrome staining indicated that NLRP3 deletion abrogated TXNIP overexpression‐induced worsening of cardiac fibrosis in obese hearts." (PMID 39604027, 2024). "In this study IL-1β and NLRP3 were more sensitive than steatosis in the detection of fibrosis." (PMID 39179677, 2024). "In mice models the NLRP3/IL1-b axis is required for the development of bleomycin induced fibrosis." (PMID 34220810, 2021). "However, little is known about the role of TXNIP and NLRP3 in post-MI fibrosis." (PMID 37850269, 2023). "Although the molecular mechanism by which Sac/Val inhibits cardiac fibrosis and inflammation following pressure unloading is poorly understood, we believe that Sac/Val protects against cardiac remodeling at least in part by suppressing NF-κB-mediated NLRP3 inflammasome activation." (PMID 32444995, 2020). "However, based on these in vivo results, it remains unclear that the anti-cardiac fibrosis activity of TP is related to which cell type of heart (cardiocytes, fibroblasts, and monocytes/macrophages, etc.), and whether TP functions through NLRP3 inflammasome." (PMID 30654511, 2019). "The present study demonstrated that levels of NLRP3 in serum and the liver were positively correlated with the METAVIR fibrosis stage and showed significant increases with the development of advanced fibrosis/cirrhosis." (PMID 36376416, 2022). "Moreover, the present study showed a high diagnostic accuracy of serum NLRP3 in detecting advanced fibrosis/cirrhosis and could be an additional marker with non-invasive fibrosis scores." (PMID 36376416, 2022). "However, the role of NLRP3 in cardiac fibrosis is still controversial and remains unclear." (PMID 32850832, 2020). "In this study, we have demonstrated that AngII-upregulated mir-21 activates the NLRP3 inflammasome by targeting Spry1, which promoted lung fibroblast collagen synthesis and exacerbated BLM-induced fibrosis." (PMID 29084974, 2017). "In addition, anoxic succinate has been shown to activate NLRP3 inflammasome through HIF-1α in an arthritic rat model, thereby exacerbating synovial fibrosis and inflammation." (PMID 39330487, 2024). "Melatonin supplementation, however, reduced cardiac fibrosis and significantly decreased the expression of IL-1α and IL-6 in WT and NLRP3−/− mice, with non-significant decline of TNFα." (PMID 34439517, 2021). "It was demonstrated that the involvement of the NLRP3 inflammasome in inducing EMT may be related to the action of TGF-β in renal, pulmonary, and hepatic models of fibrosis." (PMID 32508821, 2020).
fibrosis (continued). "Additional studies have shown that uric acid released from injured cells constitutes a major endogenous danger signal that activates the NALP3 inflammasome (also called cryopyrin or NLRP3), leading to IL-1b production as part of the host response to lung inflammation and fibrosis." (PMID 20844590, 2010).
influenza (70 papers, 2010 to 2025). An acute viral infection of the respiratory tract, occurring in isolated cases, in epidemics, or in pandemics; it is caused by serologically different strains of viruses (influenzaviruses) designated A, B, and C, has a 3-day incubation period, and usually lasts for 3 to 10 days. "The NLRP3 inflammasome pathway has been implicated in various lower respiratory diseases, including influenza, tuberculosis, bacterial pneumonia, and streptococcus pneumoniae infections, particularly in older adults." (PMID 40218944, 2025). "The NLRP3 inflammasome pathway has been implicated in various respiratory diseases, including influenza, tuberculosis, Streptococcus pneumoniae, and Staphylococcus aureus infections." (PMID 37686825, 2023). "Some pathogens (such as ADV, and influenza) can induce pyroptosis by activating the NLRP3 inflammasome, releasing IL-1β, and causing lung injury, and the process of tissue repair is maladjusted, which is related to the pathogenesis of PIBO." (PMID 36248872, 2022). "This suggests that NLRP3 activation elicits antiviral responses to control viral infection but triggers excessive inflammation and severe disease during pathogenic influenza infections." (PMID 35587190, 2022). "Increased mortality, massive cellular infiltration, and elevated NO production have been observed in Il18−/− mice infected with influenza A; with increased susceptibility to influenza reported for Nlrp3−/− and Casp1−/− mice." (PMID 35822051, 2021). "This expression profile is of interest as NLRP3 inflammasome activation has been associated with contributing to cytokine storms and severe pathology from influenza infection." (PMID 32477965, 2020). "Deletion of NLRP3 in mice causes a decrease in immune cell recruitment to the site of infection and poor outcomes when infected with influenza." (PMID 32477965, 2020). "Nlrp3−/− and Casp1−/− mice were more susceptible to influenza infection, with decreased neutrophil and monocyte recruitment and an associated reduction in cytokine and chemokine production." (PMID 29552008, 2018). "This outcome is similar to observations of influenza infection in which IL-1R and NLRP3-inflammasome deficient animals display defective CD4+ and CD8+ T lymphocyte responses in the absence of increased inflammation." (PMID 23209411, 2012). "Additionally, findings from another investigation highlighted how PM2.5 compromised innate immune responses, rendering individuals susceptible to influenza by suppressing critical factors like the NLRP3 inflammasome and interferon-beta (IFN-β) expression." (PMID 40291836, 2025). "In addition, influenza directly activates NLRP3 inflammasomes, which are implicated in fibrosis." (PMID 30937213, 2019). "The activation of NF‐κB, combined with influenza‐related damage—associated molecular pattern (DAMP) and viral components as signals, can fully activate the NLRP3 inflammasome, which can release more inflammatory factors and worsen inflammation." (PMID 40757669, 2025). "Using B cell specific ablation of IL-1β production and IL-1β signaling we further confirm that, GC B cells are the primary source of vital IL-1β within the GC and that IL-1β processing by GC B cells post influenza infection is driven by NLRP3 inflammasomes." (PMID 40825032, 2025). "Our observation of IL-1β production by B cells lead us to investigate if B cell intrinsic IL-1β and NLRP3 significantly impacted GCs post influenza infection." (PMID 40825032, 2025). "The requirement for B cell derived NLRP3, post influenza infection, further supports NLRP3 activity as a mechanism of IL-1β production in B cells." (PMID 40825032, 2025). "For example, Influenza A Virus (IAV) infection triggers the activation of NLRP3 inflammasomes and an inflammatory response." (PMID 40005815, 2025).